GIP (gastric inhibitory polypeptide)
Diseases named in the same sentence as GIP in open-access papers (continued):
Sharing a sentence is not in itself a finding about the gene and the disease.
type 2 diabetes (continued). "Tirzepatide is an innovative dual glucose-dependent insulinotropic polypeptide (GIP) and glucagon-like peptide-1 (GLP-1) receptor agonist approved for type II diabetes therapy, improving glycemic control to a greater extent than selective GLP-1 receptor agonists." (PMID 39795860, 2024). "For many years, GIP was neglected as a therapeutic target compared with GLP-1, as it was relatively ineffective at stimulating glucose dependent insulin release in patients with type 2 diabetes (T2D) when infused continuously." (PMID 38653401, 2024). "Tirzepatide—a dual action, once-weekly GIP/GLP1-RA, also revealed significant weight loss in obese patients with or without type 2 diabetes." (PMID 38408098, 2024). "Tirzepatide is a novel once-weekly glucose-dependent insulinotropic polypeptide/glucagon-like peptide-1 (GIP-1/GPL-1) receptor dual agonist, which recently has been approved as an adjunct to diet and exercise to improve glycemic control in type 2 diabetes." (PMID 38791525, 2024). "Tirzepatide, a newly developed dual glucose-dependent insulinotropic peptide (GIP) and glucagon-like peptide-1 (GLP-1) receptor agonist, has received approval for treating type 2 diabetes (T2D) and is currently being studied for its potential in long-term weight control." (PMID 38850440, 2024). "Recently, two novel agents have become available to treat patients with type 2 diabetes: finerenone, a non-steroidal mineralocorticoid receptor antagonist, and tirzepatide, a dual glucose dependent insulinotropic polypeptide (GIP)/GLP-1 receptor agonist." (PMID 37024129, 2023). "Incretin hormones (GIP and GLP-1) play an important role in the pathophysiology (reduced incretin effect) and progression (given the deterioration of postprandial glycaemic control as a result of the reduced incretin effect) of type 2 diabetes." (PMID 37430117, 2023). "The safety and tolerability of multiple and ascending doses of the triple receptor agonist of GLP-1, GIP, and glucagon LY3437943 was evaluated in 72 subjects with type 2 diabetes during 12 wk of treatment in a phase 1 double-blind, randomized, multicenter study." (PMID 37729025, 2023). "Tirzepatide is a promising drug with dual-acting glucose-dependent insulinotropic polypeptide (GIP) and glucagon-like peptide 1 (GLP-1) receptor activation that has revolutionized the treatment of type 2 diabetes mellitus (T2DM) as an adjunct to diet and exercise." (PMID 37265914, 2023). "The first peptide to attract attention was GIP, soon followed by GLP-1 because of its more suitable features as a pharmacological agent for improvement of glucose control and body-weight reduction in people with type 2 diabetes." (PMID 37542009, 2023). "The question arises whether the ability of GIP and/or GLP-1 to augment glucose-induced insulin secretion translates into an ability to lower plasma glucose in individuals with type 2 diabetes." (PMID 37430117, 2023). "Indeed, there are now several dual GIP/GLP-1 receptor agonists in clinical development, including tirzepatide, which was approved by the FDA and EMA for the treatment of type 2 diabetes in 2022." (PMID 37209227, 2023). "When administering exogenous porcine GIP, C-peptide levels rose slightly in those with type 2 diabetes, but plasma glucose levels did not change." (PMID 37430117, 2023). "Glucagon from α-cells was found to be stimulated by GIP in hyperglycemia of Type 2 diabetics, but not in healthy people." (PMID 36014921, 2022). "Mechanisms of glucose-stimulated GLP-1 and GIP secretion have been intensively investigated as glucose is a potent secretagogue and there is interest in understanding the role of both incretin hormones in the pathology and therapeutics of Type 2 diabetes (T2D)." (PMID 33803183, 2021).
type 2 diabetes (continued). "With regards to type 2 diabetes mellitus, Gault et al67 initially indicated that a GLP-1 and GIP preparation, that combinedlong-acting acylated version of the parent peptides, displayed enhancedglucose-lowering and insulinotropic actions in animal models of diabetes." (PMID 34588834, 2021). "The combination of insulinotropic actions of GIP with the favorable cardiovascular outcomes and weight reduction of GLP-1 may offer superior glycemic control in the treatment of diabetes mellitus type II." (PMID 34577569, 2021). "Gliptins constitute a class of drugs increasingly used for the treatment of type 2 diabetes mellitus, inhibiting dipeptidyl peptidase 4 (DPP4), the enzyme that inactivates the incretin hormones such as glucagon-like peptide 1 (GLP1) and glucose dependent insulinotropic polypeptide (GIP)." (PMID 34577104, 2021). "However, whereas GLP-1 also inhibits appetite and food intake and improves glucose regulation in patients with type 2 diabetes (T2DM), GIP seems to be devoid of these activities, although the 2 hormones as well as their receptors are highly related." (PMID 32459834, 2020). "As inhibition of DPP-4 prolongs the life of incretins (GLP-1 and GIP), which in turn induce insulin secretion, many DPP-4 inhibitors like sitagliptin and vildagliptin are emerging as powerful adjuncts in the treatment of type 2 diabetes." (PMID 32282828, 2020). "Unlike GIP, this peptide had preserved effects in patients with type 2 diabetes and it was soon documented to have powerful antidiabetic effects in clinical studies." (PMID 31080438, 2019). "The effects of short-term GLP-1 and GIP co-infusion have been investigated in both non-diabetic individuals and patients with type 2 diabetes." (PMID 31443356, 2019). "In human islets from non-diabetic donors and donors with type 2 diabetes, acute exposure to GIP has been reported to be superior to acute exposure with equimolar amounts of GLP-1 in terms of insulin release." (PMID 31443356, 2019). "The incretin concept was later developed further by identifying the gut hormones glucose-dependent insulinotropic polypeptide (GIP) and glucagon-like peptide-1 (GLP-1) as main incretin hormones and the development of GLP-1 as a potential treatment of type 2 diabetes." (PMID 31275243, 2019). "In non-diabetic individuals, GIP potentiates postprandial insulin secretion, but this effect is severely diminished or even absent in people with type 2 diabetes." (PMID 31443356, 2019). "Our group has studied the separate and combined effects of GIP, GLP-1 and GLP-2 (the latter known to be glucagonotropic but without any notable effect on insulin secretion) on glucagon secretion in 10 patients with type 2 diabetes." (PMID 31443356, 2019). "As well as in this paper, Xen amplifies the effects of GIP on insulin, glucagon, and pancreatic polypeptide release during graded glucose infusions in humans without type 2 diabetes mellitus." (PMID 29466430, 2018). "However, recent study shows that there is a synergistic effect of GIP and GLP-1 co-agonists in weight lowering and glycemic improvement in patients with type 2 diabetes than mono-agonist." (PMID 29997575, 2018). "In type 2 diabetes, the insulinotropic effect of GLP-1 remains relatively intact, although that of GIP is markedly diminished, which may account for the diminished incretin effect in this group." (PMID 30319553, 2018). "Despite encouraging preclinical data and the success of DPP-4 inhibitors, progression of enzyme-resistant GIP-based drugs to the type 2 diabetes clinic is lacking." (PMID 28004148, 2017). "In contrast, pharmacological augmentation of circulating GIP levels fails to evoke an effective increase in insulin secretion in patients with type 2 diabetes." (PMID 28004148, 2017). "It is known that GIP does not modulate glucose-dependent insulin secretion in type 2 diabetes, even at supraphysiological (pharmacological) plasma levels." (PMID 29041949, 2017).
type 2 diabetes (continued). "Patients with type 2 diabetes have been found to have elevated basal GIP in comparison with people who do not have diabetes." (PMID 28753646, 2017). "Similarly, intake of olive oil has been found to increase the production of both GIP and GLP-1 in healthy individuals and GLP-1 in individuals with type 2 diabetes compared with an isoenergetic intake of butter." (PMID 27623947, 2016). "Interestingly, levels of GIP and GLP-1 were elevated by FR and MR in type 2 diabetes and controls, when compared with RF." (PMID 26704625, 2016). "In conclusion, patients with type 2 diabetes and healthy controls display significant post-prandial TSH suppression to a series of meal-related stimuli, but independently of the degree of gallbladder emptying and of the gut hormones GIP, GLP1 and GLP2." (PMID 25277744, 2014). "Previous studies have indicated that whereas GLP-1 is strongly insulinotropic in patients with Type II diabetes mellitus, the effect of GIP is much weaker or absent." (PMID 23590862, 2013). "Additionally, patients with type 2 diabetes secret smaller amount of glucagon-like peptide–1 (GLP-1) and have a decreased insulinotropic effect of glucose dependent insulinotropic polypeptide (GIP)." (PMID 23452780, 2013). "Plasma levels of GIP appear normal to increased in subjects with type 2 diabetes, whereas meal-stimulated plasma levels of GLP-1 are modestly but significantly diminished in patients with impaired glucose tolerance and in subjects with type 2 diabetes." (PMID 20470376, 2010). "In addition to these, evidences from recent studies also suggest a role for gastrointestinal hormones like incretins which include GIP and glucagon-like peptide -1(GLP-1) towards the manifestation of type 2 diabetes." (PMID 20673334, 2010). "In type 2 diabetes, GIP no longer modulates glucose-dependent insulin secretion, even at supraphysiological plasma levels, and therefore GIP incompetence is detrimental to pancreatic beta-cell function, especially after eating." (PMID 19785737, 2009). "GLP-1 RAs, including semaglutide and liraglutide, have shown cardiovascular benefits in patients with type 2 diabetes, and emerging evidence suggests tirzepatide—a dual GLP-1/GIP agonist—may offer even greater cardio protection, including among cancer patients." (PMID 40869064, 2025). "Glucagon-like peptide-1 (GLP-1) receptor agonists, dual gastric inhibitory polypeptide (GIP)/GLP-1 receptor agonists, and pioglitazone have demonstrated efficacy in decreasing hepatic steatosis, resolving MASH, and reducing fibrosis in patients with type 2 diabetes and MASLD or MASH." (PMID 41366647, 2025). "In individuals with type 2 diabetes mellitus (T2DM), the incretin effect is markedly impaired, with GLP-1 activity being preserved but diminished, and GIP activity being significantly reduced." (PMID 41303737, 2025). "The GIP/GLP-1 dual agonist, tirzepatide, reduced liver fat and improved biomarkers of MASH and fibrosis in patients with type 2 diabetes (T2D); a phase 2 trial in MASH is ongoing." (PMID 38858523, 2024). "Glucagon-like peptide-1 (GLP-1) and glucose-dependent insulinotropic polypeptide/GLP-1 (GIP/GLP-1) receptor agonists are well-established in various clinical settings, including glucose control in type 2 diabetes and weight loss in people with and without diabetes." (PMID 39768911, 2024). "The biological effects of GIP on β-cells in the pancreas are mainly regulated by the high-affinity receptor for GIP (GIPR) and a novel dual GIP and glucagon-like peptide-1 (GLP-1) receptor agonist, tirzepatide, has been developed for the treatment of patients with type 2 diabetes." (PMID 39273671, 2024). "In this review, we summarise current knowledge regarding the secretion and insulinotropic action of GIP and GLP-1, their contribution to the incretin effect, and their effects on glucagon secretion, gastric emptying, appetite and energy intake in people with type 2 diabetes and healthy individuals." (PMID 37430117, 2023).
type 2 diabetes (continued). "The addition of a GIP agonist to a GLP-1agonist has been hypothesized to significantly potentiate the weight-losing and glycemia control effect, which might offer a new therapeutic option in the treatment of type 2 diabetes." (PMID 37904255, 2023). "Interestingly, the suppression of glucagon by exogenous GLP-1 in type 2 diabetes was antagonised by concomitant administration of GIP, which alone did not significantly affect plasma glucagon concentrations." (PMID 37430117, 2023). "A study comparing the effects of GIP and GLP-1 in perfused pancreases from healthy rats and a streptozotocin-induced rat model of diabetes suggested a similar impairment regarding the insulinotropic actions of GLP-1 as previously shown for GIP in a model of human type 2 diabetes." (PMID 37430117, 2023). "GIP does not affect gastric emptying in healthy individuals or those with type 2 diabetes." (PMID 37430117, 2023). "Generally speaking, the incretin effect is reduced or absent in type 2 diabetes because of the impaired insulinotropic action of endogenously secreted GIP, as can be inferred from the reduced insulinotropic activity of exogenously administered GIP." (PMID 37430117, 2023). "However, in previous studies on diabetic patients, GIP did not influence the overall effect of the combination in type 2 diabetes patients." (PMID 36362984, 2022). "Tirzepatide is a dual glucagon-like peptide-1 (GLP-1) and glucose-dependent insulinotropic polypeptide (GIP) receptor agonist and a promising therapy for type 2 diabetes mellitus (T2DM)." (PMID 35745639, 2022). "Moreover, the impact of incretin hormones such as GLP1 and GIP on both insulin secretion and satiety has been widely reported, with GLP1-agonists now being regularly employed in the treatment of type 2 diabetes mellitus." (PMID 36281448, 2022). "Currently, there is a lack of clinically approvedtherapies aimed at restoring GIP bioactivity in type 2 diabetes mellitus, thusxenin could hold real promise as a diabetes therapy." (PMID 34588834, 2021). "Similar results were obtained when using variant–exposure associations for HbA1c levels rather than for type 2 diabetes liability (Pearson correlation of the MR β estimates = 0.99), and when using missense variant rs2291725 in GIP or eQTL variant rs12709891 in GIPR." (PMID 34505161, 2021). "The lack of insulinotropic effects of GIP in type 2 diabetes, as seen in acute infusion studies, could depend on hyperglycemia." (PMID 35054422, 2021). "Given xenin has confirmed GIP-potentiatingactions, the combination of therapies that increase xenin bioactivity alongsideestablished DPP-4 inhibitor drugs clearly warrants further consideration as a noveltherapeutic option in the management of type 2 diabetes mellitus in humans." (PMID 34588834, 2021). "DPP4 cleavage of the incretin peptides, glucagon-like peptide-1 (GLP-1) and gastric inhibitory polypeptide (GIP), have led to the development of DPP4 selective inhibitors as a successful type 2 diabetes mellitus (T2DM) therapy." (PMID 33218025, 2020). "It will be important to identify the neurotransmitters or neuropeptides that mediate the effects of Xen on insulin and glucagon release in humans because signaling pathways initiated by Xen rather than GIP fail early during the development of type 2 diabetes mellitus." (PMID 29466430, 2018). "Our earlier study showed that GIP transiently increases plasma glucagon levels as well as ISRs over the first 40 minutes of the graded glucose infusion and these responses were amplified by Xen only in subjects without type 2 diabetes mellitus." (PMID 29466430, 2018). "Further study on GIP gene variants and CAD risk could be conducted in Chinese population with or without type 2 diabetes to prove the hypothesis." (PMID 28840129, 2017).
type 2 diabetes (continued). "Since the incretin hormones, glucagon-like peptide-1 and glucose-dependent insulinotropic polypeptide (GIP), are major regulators of post-prandial insulin secretion, inhibition of DPP4 by the gliptin family of drugs has gained considerable interest for the therapy of type 2 diabetic patients." (PMID 26284071, 2015). "GPR40 full agonists AM-1638 and AM-6226 stimulate GLP-1 and GIP secretion from intestinal enteroendocrine cells and increase GSIS from pancreatic islets, leading to enhanced glucose control in the high fat fed, streptozotocin treated and NONcNZO10/LtJ mouse models of type 2 diabetes." (PMID 23056280, 2012). "Given that, on the contrary, collected evidence suggests that GIP concentrations decrease post-surgery, the lower-intestinal dumping hypothesis would seem to describe the mechanism most likely to produce the observed normalization of Type 2 Diabetes Mellitus (T2DM) after bariatric surgery." (PMID 22587410, 2012). "Sitagliptin is reported to decrease the total GIP level, but this may not be applicable to all patients with type 2 diabetes." (PMID 22189184, 2011). "Incretins, glucose-dependent insulinotropic polypeptide (GIP) and glucagon-like peptide-1 (GLP-1) have been shown to improve hyperglycemia in patients with type 2 diabetes, suggesting that an enhanced capacity of GIP and GLP-1 production could be beneficial in type 2 diabetes." (PMID 41711307, 2026). "Dipeptidyl peptidase-4 inhibitors (DPP-4is) have been developed as oral antidiabetic agents in type 2 diabetes mellitus (T2DM), as they prevent the degradation of incretins such as glucagon-like peptide 1 (GLP-1) and glucose-dependent insulinotropic polypeptide (GIP)." (PMID 35164839, 2022). "Thus, Xen rather than GIP signaling to islets fails early during development of type 2 diabetes." (PMID 29466430, 2018). "Type 2 diabetes mellitus (T2DM) often requires pharmacological management, with newer agents like glucagon-like peptide-1 (GLP-1) receptor agonists (GLP-1 RA) and dual gastric inhibitory polypeptide (GIP)/GLP-1 receptor agonists offering metabolic and cardiovascular benefits." (PMID 40746803, 2025). "Previously, it was reported that postprandial GIP secretion is not reduced in Europeans with type 2 diabetes compared to those without, but GLP-1 secretion is reduced in those with type 2 diabetes." (PMID 40607157, 2024). "Tirzepatide is a dual glucose-dependent insulinotropic peptide (GIP) and glucagon-like peptide-1 receptor agonist (GLP-1 RA) approved by the US Food and Drug Administration in May 2022 for patients with type 2 diabetes mellitus (T2DM)." (PMID 36789109, 2023). "The partially preserved insulinotropic activity of GLP-1 in type 2 diabetes is probably not sufficient to support a sizeable incretin effect, as GLP-1 responses after oral glucose are smaller than those for GIP." (PMID 37430117, 2023). "Some earlier studies suggested the presence of hypersecretion of GIP and hyposecretion of GLP-1 in type 2 diabetes, but meta-analyses show no apparent systematic differences in secretion between people with type 2 diabetes and healthy individuals." (PMID 37430117, 2023). "In patients with type 2 diabetes, GLP-1 and GIP secretion are relatively normal, but their ability to stimulate insulin secretion is decreased by about 50% for GIP and 30% for GLP-1 compared to subjects without diabetes." (PMID 38067196, 2023). "The first significant factor identified was the duodenal glucose-dependent insulinotropic polypeptide, GIP, which however, turned out not to stimulate insulin secretion in patients with type 2 diabetes." (PMID 31080438, 2019). "A number of key studies have suggested that GIP might promote weight gain: global germline GIPR knockout mice on a HFD display reduced body weight and maintain insulin sensitivity, whilst in patients with type 2 diabetes (T2D), the insulinotropic effect of GIP is impaired." (PMID 38653401, 2024).